MGMT (O-6-methylguanine-DNA methyltransferase)
Diseases named in the same sentence as MGMT in open-access papers (continued):
Sharing a sentence is not in itself a finding about the gene and the disease.
oligodendroglioma (56 papers, 2008 to 2025). A well-differentiated (WHO grade II), diffusely infiltrating neuroglial tumor, typically located in the cerebral hemispheres. "Conversely, the C3 subtype was characterized by a predominance of oligodendrogliomas, 1p/19q co-deletion and MGMT promoter methylation which features associated with better clinical outcomes." (PMID 40307749, 2025). "Particularly, WHO grade II, 1p/19q co-deletion, IDH mutation, MGMT promoter methylation, and oligodendroglioma had decreased m5CrLS scores." (PMID 35309316, 2022). "DNA Methylation profiling showed methylated MGMT promoter, 1p and 19q losses in copy number profiling and allocated the tumor to the methylation class of oligodendroglioma IDH mutated 1p/19q co-deleted." (PMID 35018523, 2022). "The frequency of IDH mutations and MGMT promoter methylation was similar in both the “astrocytic” and oligodendroglioma groups." (PMID 25991674, 2015). "In the univariate adjusted ORs, being young (OR 2.56, 95% CI 1.48–4.43), being female (OR 1.52, 95% CI 1.11–2.08), having IDH1 mutation (OR 15.92, 95% CI 7.30–34.75) and an oligodendroglioma diagnosis (OR 6.20, 95% CI 1.33–28.88) were associated with MGMT methylation." (PMID 39767640, 2024). "pTERT mutations and MGMT methylation were detected in grade 2 and 3 oligodendroglioma." (PMID 38404571, 2024). "In the univariate adjusted ORs, being younger than 39 years (OR 2.56, 95% CI 1.48–4.43), female (OR 1.52, 95% CI 1.11–2.08), having IDH1 mutation (OR 15.92, 95% CI 7.30–34.75) and an oligodendroglioma diagnosis (OR 6.20, 95% CI 1.33–28.88) were associated with MGMT methylation." (PMID 39767640, 2024). "Diseases associated with MGMT include oligodendroglioma and gliosarcoma." (PMID 37019990, 2023). "Our data may suggest that MGMT methylation is associated with cervical cancer progression, as a previous longitudinal study showed that MGMT promoter methylation is particularly pronounced during tumor progression in oligodendroglioma." (PMID 37834832, 2023). "The tumor was pathophysiologically characterized as a WHO grade 2 oligodendroglioma with an IDH (isocitrate dehydrogenase) mutation, 1p19q codeletion, and MGMT (O6-methylguanine-DNA methyltransferase) gene promoter methylation." (PMID 39330015, 2024). "All 29 IDHmut oligodendrogliomas analyzed by DNA methylation array tested positive for MGMT promoter methylation, even with VAFs as low as 0.18." (PMID 37919784, 2023). "For IDHmut oligodendroglioma, mean MGMT score differences above and below the regression cutoff (IDH VAF = 0.30) did reach statistical significance (p < 0.0001)." (PMID 37919784, 2023). "A methylated MGMT promotor was observed in near all primary oligodendrogliomas and MGMT remained methylated at recurrence." (PMID 36739454, 2023). "Patient 1 was a man in his mid-30s who received an initial diagnosis of WHO grade II oligodendroglioma with IDH mutated and MGMT unmethylated status in March 2016." (PMID 35923675, 2022). "Mean DNA methylation levels at differentially methylated positions were significantly reduced in oligosarcomas compared to oligodendrogliomas (online resource), while the MGMT promoter was methylated in all cases." (PMID 34967922, 2022). "MGMT promoter was methylated in 58/60 oligodendroglial tumours (5 low, 21 intermediate, and 32 high level), in 4 IDH-mutant astrocytic (2 intermediate and 2 high level), and in 2 IDH-wt (1 low and 1 intermediate level)." (PMID 34165590, 2021). "Fourth row (panel δ) presents a patient with WHO III° oligodendroglioma (MGMT−, IDH1+, LOH1p/19q+), which was classified as post-treatment related effect." (PMID 31601829, 2019). "First row (panel α) demonstrates a patient with a treated WHO III° oligodendroglioma (MGMT+, IDH1+, LOH1p/19q+), originally classified as relapse." (PMID 31601829, 2019). "Third row (panel γ) shows recurrence of a WHO III° oligodendroglioma (MGMT−, IDH1−), originally categorised as treatment-related effect." (PMID 31601829, 2019).
oligodendroglioma (continued). "However, its effectiveness is limited in the treatment of oligodendrogliomas or O6-methylguanine-DNA-methyltransferase (MGMT) promoter-methylated GBM." (PMID 36307808, 2022). "MGMT-tested patients were also more likely to receive chemotherapy compared to untested patients, which is comparable to our findings on adjuvant treatment for oligodendroglioma/oligoastrocytoma patients." (PMID 34858822, 2021). "In our series, MGMT promoter methylation was also stable among tissues from the same patient, although a previous study suggested that there is clonal heterogeneity of MGMT promoter methylation even in oligodendroglioma." (PMID 28270234, 2017). "Frequent promoter hypermethylation and reduced expression of the MGMT gene in oligodendrogliomas and consecutive impairment of MGMT-mediated DNA repair might in part contribute to the chemosensitivity of these neoplasms." (PMID 19333441, 2009). "The observation that MGMT promoter hypermethylation is common in oligodendrogliomas with losses on 1p and 19q may point to at least one possible mechanism contributing to the chemosensitivity of these tumors." (PMID 19333441, 2009). "The methylation of the MGMT promoter was correlated with younger patients who were aged less than 39 years (OR 2.56, 95% CI 1.48–4.43), female (OR 1.52, 95% CI 1.11–2.08) or had an IDH1 mutation (OR 15.92, 95% CI 7.30–34.75) and an oligodendroglioma diagnosis (OR 6.20, 95% CI 1.33–28.88)." (PMID 39767640, 2024). "Conversely, inflammation-low subtypes mainly included low mortality, methylated MGMT promoter status, IDH mutant status, 1p19q codeletion status, WHO II grade, and oligodendroglioma histology." (PMID 36180938, 2022). "Prognostic features in non-TCGA IDH1/2-mutant 1p/19q-codeleted oligodendrogliomas were rare and no molecular alterations significantly influenced survival, including MGMT-methylation status." (PMID 39164213, 2025). "MGMT promoter methylation is a late event during oligodendroglioma evolution, and their chemosensitivity is not necessarily related to MGMT methylation status." (PMID 37533228, 2023). "Virtually all 1p/19q codeleted oligodendrogliomas show G-CIMP and MGMT promoter methylation." (PMID 25943885, 2015). "MGMT methylation is not a commonly reported characteristic of human oligodendroglioma." (PMID 40417366, 2025). "While nearly all oligodendrogliomas are MGMT-methylated, this routine testing might not be necessary." (PMID 39767640, 2024). "In this study, the number of patients with oligodendroglioma was small, and no patients had the MGMT unmethylated status; therefore, survival analyses could not be performed." (PMID 38404571, 2024).
gastric cancer (39 papers, 2002 to 2025). A primary or metastatic malignant neoplasm involving the stomach. "Again, low MGMT expression in gastric cancer patients is associated with serosal invasion, advanced-stage disease, lymph node positivity, undifferentiated histopathological type, and poor prognosis." (PMID 33976347, 2021). "For instance, a study conducted in Poland found that XRCC1, XPD and MGMT polymorphisms modified the magnitude of risk associated with low intake of fruits or vegetables and smoking for gastric cancer." (PMID 29020930, 2017). "Loss of MGMT expression by promoter methylation has been reported in many tumor types, including gastric cancer." (PMID 27824946, 2016). "Of these genes, promoter hypermethylation of CDH1 and MGMT was associated with worse outcomes after surgery for gastric cancer." (PMID 23179365, 2013). "In our gastric cancer cases, the loss of MGMT expression is significantly associated with microsatellite instability (P=0.041) as well as with hMLH1 expression (P=0.002, data not shown)." (PMID 12085181, 2002). "In summary, we suggest that during gastric carcinoma progression, loss of expression at the MGMT gene is frequently caused by promoter hypermethylation of CpG islands and that this is significantly associated with tumour progression and prognosis." (PMID 12085181, 2002). "To investigate the association between the loss of MGMT expression and the clinicopathologic characteristics, we carried out immunohistochemistry using six tissue array blocks containing 315 consecutive gastric carcinomas with the follow-up data." (PMID 12085181, 2002). "In the present study, promoter methylation was detected in 14.1% of gastric carcinomas and a loss of MGMT expression was found in 11.4–13.3% of tumours." (PMID 12085181, 2002). "In gastric cancer, aberrant methylation occurs in genes associated with DNA repair (such as hMLH1 and MGMT), transcriptional regulation (such as HLTF), cell growth/differentiation (such as HoxD10 and NDRG2), cell cycle (such as p16), and apoptosis (such as BNIP3)." (PMID 37508393, 2023). "Promoter methylation of MGMT is related to gastric cancer risk, distant metastasis, and lymph node metastasis, which indicates that MGMT promoter methylation may play an important role in gastric cancer development." (PMID 28418867, 2017). "Our findings showed that the MGMT methylation status was significantly associated with the risk of GC (OR = 3.34, 95% CI = 2.34–4.76, P < 0.001), suggesting that MGMT methylation can be crucial for the carcinogenesis of gastric cancer." (PMID 27824946, 2016). "We examined the loss of expression and the promoter methylation of MGMT in 149 gastric carcinomas and 11 gastric cancer cell lines and investigated an association with loss of expression and clinicopathological characteristics in consecutive gastric carcinomas." (PMID 12085181, 2002). "In gastric cancer, early upregulation of MGMT promotes DNA damage repair; however, hypermethylation of its promoter at a later stage leads to reduced MGMT expression." (PMID 41211438, 2025). "High MGMT expression and low ATG4B expression are significantly associated with survival in gastric cancer." (PMID 38254819, 2024). "Cisplatin, on the other hand, counteracts MGMT-mediated autophagy suppression, thereby reducing chemosensitivity in gastric cancer." (PMID 38254819, 2024). "It is noteworthy that the impact of MGMT levels appears to differ in ovarian cancer and gastric cancer." (PMID 38254819, 2024). "This increased methylation activity led to hypermethylation and inactivation of the tumor suppressor gene O-6-methylguanine-DNA methyltransferase (MGMT) in stomach epithelial cells that can contribute to the development of gastric cancer." (PMID 36769214, 2023). "Cancer drugs based on the killing properties of O6-MeGua such as temozolomide are common in colon/gastric cancer chemotherapy particularly for those tumors with methylation of MGMT." (PMID 29156686, 2017).
gastric cancer (continued). "The results of our study indicate an inverse correlation between the methylation of the MLH1 and MGMT genes in gastric cancer tissues when the tumor was located in the lower third of the stomach (coefficient, –0.48; p = 0.01)." (PMID 26810771, 2016). "Scientific publications indicate that the methylation of the MGMT gene promoter is one of the pathogenetic pathways in gastric cancer." (PMID 26810771, 2016). "The result suggested that MGMT methylation had a trend toward less frequency in male gastric cancer patients compared with female gastric cancer patients (OR = 0.76, 95% CI = 0.56–1.03, P = 0.077)." (PMID 27824946, 2016). "The hypermethylation of the DNA repair protein O6-methylguanine DNA methyltransferase (MGMT) has been found in 31% of gastric cancer cases." (PMID 25997695, 2015). "Our study showed that hypermethylation of P16 and MGMT genes was related with TNM stage in gastric cancer tissues." (PMID 24550949, 2013). "The findings from the present study indicated that a higher hypermethylation of P16, MGMT and hMLH1 gene in gastric cancer tissues than remote-normal-appearing gastric tissues." (PMID 24550949, 2013). "The proportions of DNA hypermethylation in P16, MGMT and hMLH1 genes in gastric cancer tissues were 75.2% (242/322), 27.6% (89/322) and 5.3% (17/322), respectively." (PMID 24550949, 2013). "Further large-scale studies are required to elucidate the association between P16, MGMT and HMLH1 and risk of gastric cancer." (PMID 24550949, 2013). "In gastric cancer it has been previously reported that a correlation between MGMT methylation and lymph node metastasis exists." (PMID 22246327, 2012). "Furthermore, it has been shown that MGMT plays a role in the chemosensitivity of cisplatin in gastric cancer." (PMID 38255825, 2024). "This introduces a fresh perspective on treating gastric cancer by inhibiting MGMT." (PMID 38255825, 2024). "In addition, MGMT methylation-mediated loss of expression has been frequently observed in HCC tumor samples, non-small cell lung cancer, and gastric cancer." (PMID 35723009, 2022). "A possible explanation of this opposition may lie in ethnic and environmental factors and the disease stage: a meta-analysis in gastric cancer shows heterogeneity on MGMT methylation between Asian and Caucasian populations." (PMID 29805743, 2018). "In addition, the methylation frequency of the MGMT promoter was inconsistent in gastric cancer, with a range from 7% to 70%." (PMID 27824946, 2016). "Hypermethylation of P16 and MGMT genes was related with TNM stage in gastric cancer tissues." (PMID 24550949, 2013). "Therefore, we hypothesized that MGMT promoter methylation status might play a role in the development of gastric cancer." (PMID 27824946, 2016). "A study discovered that BanxiaXiexin decoction modulates MGMT expression by affecting IL6/JAK/STAT3-mediated PDL1 activity, thereby influencing the drug sensitivity of gastric cancer cells." (PMID 38255825, 2024). "It has recently been established that in gastric cancer cells, PGE2 induces DNMT3B expression and activity, which in turn results in a higher level of MGMT promoter methylation." (PMID 33941107, 2021). "The methyltransferase MGMT inhibits the expression of ATG4B, thereby inhibiting autophagy and reducing the chemosensitivity of cisplatin in gastric cancer (GC)." (PMID 33604190, 2021). "Gastric cancer cells over-expressing Polβ (common trait in stomach tumors) present increased resistance to 6-TG and also to MMS upon inhibition of MGMT by O6-BzGua (that is in clinical trials)." (PMID 29156686, 2017). "The relationship between MGMT promoter methylation and gastric cancer (GC) remains inconsistent." (PMID 27824946, 2016). "In gastric cancer, a large number of genes (e.g., CDKN2A, CDK2AP2, CDH1, MGMT, RASSF1, RUNX3, and DLC1) have been shown to be suppressed by CpG island hypermethylation." (PMID 23179365, 2013).
gastric cancer (continued). "Notably, gastric cancer and CRC share many aberrant DNA methylations, including SEPT9, MGMT, and SDC2." (PMID 38318978, 2024). "In a study of 62 gastric cancer tissue samples, KRAS mutations were detected in only one (1.6%) sample and MGMT methylation was detected in 13 (21%) samples, and no connection was shown between KRAS mutations and MGMT methylation." (PMID 27643594, 2016). "In conclusion, we found the aberrant hypermethylation of cancer-related genes, such as P16, MGMT and HMLH1, could be predictive biomarkers for detecting of gastric cancer." (PMID 24550949, 2013). "RASSF1A, p14ARF, and MGMT; CHRNA3, DOK1, and GNMT; p16, hMLH1, MINT1, MINT2, MINT12, MINT25, and MINT31; APC, CDH1, MHL1, CDKN2A, CDKN2B, and RUNX3; CDH1; DKK3; PTEN; MGMT; TFPI2; CACNA2D3; PCDH10; SOX2; MAL; and COX2 were previously reported to be hypermethylated in gastric cancer." (PMID 26121593, 2015).
colon carcinoma (35 papers, 2004 to 2025). "A landmark study demonstrated that MGMT causes a threshold in NOC-induced colon cancer formation at low methylation dose levels." (PMID 36902118, 2023). "One year later, the same group documented a link between loss of MGMT and G to A mutations in K-ras gene in colon cancer, which was followed by a report showing the similar findings in gastric cancers." (PMID 24151575, 2013). "Assays targeting CpG islands of LINE-1, MLH1 and MGMT were chosen since aberrant methylation of this retro-transposon and these genes is implicated in colon cancers." (PMID 22243995, 2012). "Therefore, it has been proposed that MGMT status might be a useful marker for early detection and risk assessment in sporadic colon cancers." (PMID 24151575, 2013). "While colon cancers are known to harbor methylation in many genes in addition to the MGMT, MGMT is found frequently epimutated in WBC, indicating a constitutional origin." (PMID 39980037, 2025). "Based on previous studies suggesting a correlation between MGMT methylation and advanced age in colon cancer patients, we specifically analyzed this subgroup." (PMID 39594133, 2024). "One-third of the BRCA1- and MGMT-methylation-positive patients had a strong family history of cancer, including breast, ovarian, and colon cancers." (PMID 38542081, 2024). "Data obtained in different mouse models also revealed that MGMT protects against methylation-induced liver cancer, lung cancer, thymic lymphomas, and colon cancer." (PMID 36902118, 2023). "Colon tumor induction upon AOM/DSS challenge was potentiated in MGMT and PARP-1 double knockout mice, demonstrating the important roles of these proteins in the protection against NOC-induced genomic instability and cancer." (PMID 36902118, 2023). "Experimental data support this possibility, because 5-FU cytotoxicity was enhanced by O6-benzylguanine-induced MGMT depletion in colon cancer cells with high MGMT expression." (PMID 25015560, 2014). "Our earlier studies in the AOM model provided evidence that Se-enriched milk protein at 1ppm prevents colon cancer by activating the acute apoptotic response; and 0.5% green tea enhances MGMT expression (unpublished data) in rat colon." (PMID 23717604, 2013). "MGMT methylation has been detected in the aberrant crypt foci, which are the earliest precursor lesions in colon cancer development suggesting that MGMT methylation is an early event in neoplastic pathway." (PMID 24151575, 2013). "For example it has been shown that MGMT protects body against N-nitroso compounds, known to induce colon cancer by methylating the DNA." (PMID 24151575, 2013). "Increased MGMT methylation in the normal mucosa of patients with colon cancers showing MGMT methylation was also reported recently." (PMID 16421593, 2006). "Also in the present study, some colon cancer cases showed MGMT methylation in both mucosa (especially right-sided) and corresponding tumor." (PMID 40357388, 2025). "However, the frequency of tumors with MLH1, MGMT, and p16INK4a hypermethylation agreed with previously published reports, indicating that the patients constituted a representative colon cancer cohort with regard to methylation profiles." (PMID 40357388, 2025). "In addition, O6-methylguanine-DNA methyltransferase (MGMT) was previously reported to harbor cancer-specific promoter methylation in multiple types of cancer including colon cancer, so we excluded MGMT from our further analysis (52 -2 = 50)." (PMID 19662090, 2009). "Interestingly, SEPT9 and MGMT methylation levels were significantly lower in rectal cancer patients that underwent neoadjuvant treatment, which is in line with studies in which ionizing radiation exposure induced global hypomethylation, including for colon cancer." (PMID 29486770, 2018).